INS (insulin)
Diseases named in the same sentence as INS in open-access papers (continued):
Sharing a sentence is not in itself a finding about the gene and the disease.
Hypoglycemia (continued). "Additionally, SMPG measurements were not embedded into the LEADER protocol, and were likely to be more common in those with prior glucose variability, previous experience of hypoglycaemia and those on insulin therapy." (PMID 34704120, 2022). "Furthermore, inclusion of standardized insulin administration instructions in the order set should be defaulted in an effort to prevent hypoglycemia." (PMID 35917098, 2022). "Incidence of hypoglycaemia with tirzepatide was similar vs placebo and lower vs basal insulin." (PMID 35579691, 2022). "It has been reported that exogenous insulin does not inhibit endogenous insulin secretion or cause negative feedback as long as there is no insulin excess to induce hypoglycemia." (PMID 35574023, 2022). "However, frequent episode of hypoglycemia was observed in patients treated with the premixed insulin-based therapy compared with patients treated by NPH insulin-based therapy." (PMID 35617250, 2022). "The effect of S. torvum fruit extract on histopathology of pancreas has showed the regeneration of β cells of islets of Langerhans which may be responsible for increased secretion of insulin resulting in hypoglycemia." (PMID 36386935, 2022). "Some gluten-free food items may be low in carbohydrates; hence, hypoglycemia may develop after the administration of standard (unadjusted) dosages of insulin." (PMID 36615856, 2022). "Due to the insulin-independent mechanism of action of SGLT-2is, the risk of hypoglycemia with these agents is low in patients with T2D but may increase when SGLT-2is are used concomitantly with insulin or sulfonylureas (insulin secretagogues)." (PMID 36294370, 2022). "Moreover, it also impairs hepatic glucose production, as well as blunts CRR to insulin-induced hypoglycemia and 2-DG-induced glucopenia." (PMID 35619170, 2022). "Metformin does not enhance insulin release from pancreatic β cells; thus, it does not cause hypoglycaemia." (PMID 36355535, 2022). "Furthermore, hypoglycemia induced by i.p. insulin injection or during a hypoglycemic clamp led to lower glucagon secretion in AgRPAgpat5KO than in control mice." (PMID 36180454, 2022). "However, the treatment measures required to control blood glucose at the ideal level result in increased risks for hypoglycemia, particularly in patients who use insulin or insulin secretagogues." (PMID 36434039, 2022). "As an important aspect of insulin treatment, the frequency of hypoglycemia, was analyzed." (PMID 35457303, 2022). "In addition, use of DPP-4 inhibitors is associated with upper respiratory tract infection, headaches, and a potential for hypoglycemia especially if used in concert with insulin." (PMID 36148775, 2022). "Current methods to control blood sugar, including controlled diet, metformin, sulfonylurea, and insulin, have limited efficacy and are associated with potential health problems such as hypoglycemia, weight gain, and lack of sustained efficacy." (PMID 35213965, 2022). "Furthermore, recurrent insulin-induced hypoglycemia in diabetic rats leads to increased OxS in brain mitochondria." (PMID 35453666, 2022). "Furthermore, Cpt1aflox/flox mice and AgRPCpt1aKO littermates displayed identical glucose tolerance, insulin sensitivity, and glucagon response to insulin-induced hypoglycemia." (PMID 36180454, 2022). "In the case of sepsis, hypoglycemia occurs, and insulin and C-peptide concentrations are also low." (PMID 35324747, 2022). "Events of hypoglycemia were presented among 35% of patients on insulin/sulfonylurea therapy." (PMID 35406122, 2022). "Finally, improving the knowledge of diabetic patients will result in a decrease in health care costs derived from complications, hypoglycemia, ketoacidosis, foot ulcers and errors in insulin administration." (PMID 35564474, 2022).
Hypoglycemia (continued). "Indeed, conventional therapeutic management with insulin leads to an average one or two episodes of symptomatic hypoglycemia weekly and at least one episode of severe, temporarily disabling hypoglycemia per year." (PMID 35406129, 2022). "Reducing the basal insulin dose by 20% may also be recommended before a planned tournament or excessive exercise to prevent hypoglycemia." (PMID 35345701, 2022). "Non-glucose responsive mechanisms of insulin secretion, such as sulphonylureas, have been linked to the potential for hypoglycemia in humans." (PMID 36482991, 2022). "Order sets have been shown to reduce insulin errors and hypoglycemia rates." (PMID 35917098, 2022). "Therefore, accurately regulating the amount of insulin used during fasting is critical for the prevention of hypoglycemia." (PMID 36235648, 2022). "Hypoglycemia may be involved in the high incidence of falls in older adult diabetic patients on insulin therapy." (PMID 35831378, 2022). "In both cases insulin concentration was normal when measured with the Roche’s immunoassay, but was appropriately elevated when remeasured with the Advia Centaur immunoassay and a diagnosis of hypoglycemia secondary to insulin analogue administration was made." (PMID 36376919, 2022). "Furthermore, the OR of hypoglycemia events related to insulin prescription was 4.68 among all glucose-lowering drugs." (PMID 35055382, 2022). "We map out the early stages of our hypothesis as a disruptive novel approach, where we propose to use glucagon as a vasodilator to accelerate the absorption of meal boluses of insulin, besides using it conventionally to treat hypoglycaemia." (PMID 36213069, 2022). "In conclusion, dapagliflozin 10 mg treatment greatly decreased the HbA1c, insulin dosage, and body weight without increasing the risk of hypoglycemia in T1DM." (PMID 35872994, 2022). "Acute treatment of insulin that needs immediate management has certified long-lasting advantages, but the possibility of acute hypoglycemia may affect overall quality of life." (PMID 35723344, 2022). "Likewise, deletion of ACC1 in alpha-cells in mice reduced glucagon secretion at low glucose in isolated islets, and in response to fasting or insulin-induced hypoglycaemia in vivo." (PMID 35304577, 2022). "However it has been argued that methodological flaws in the protocol in terms of glucose measurement and insulin administration resulted in an excessive incidence of hypoglycemia." (PMID 35842591, 2022). "Hypoglycemia may still occur in the post-exercise phase, as increased skeletal muscle insulin sensitivity and glucose uptake can last for up to 48 hours following acute exercise." (PMID 36339413, 2022). "Metabolic evaluation of hypoglycemia showed a typical profile of hyperinsulinemic hypoglycemia (glucose 37 mg/dL [2 mmol/L], insulin 6.1 mU/L, betahydroxybutyrate [BHB] 0.15 mmol/L, plasma glucose increased from 40 to 79 mg/dL [2.22 to 4.38 mmol/L] on glucagon administration)." (PMID 35897673, 2022). "Patients who were treated with sulfonylureas and insulin were more likely to experience severe hypoglycemia, whereas patients who were treated with sodium-glucose cotransporter 2 inhibitors and those requiring insulin therapy were more likely to experience DKA or HHS." (PMID 35040969, 2022). "Also, fear of hypoglycemia is one of the main factors that hinders the issue of insulin bolus, partially because manual calculation increases its risk." (PMID 36100854, 2022). "Outcomes were HbA1c, hypoglycemia, weight gain and insulin dose in two groups." (PMID 35045841, 2022). "Thus, this study was conducted to investigate the differences in glycaemic variability and hypoglycaemia between basal insulin and premixed insulin by using CGM." (PMID 35574003, 2022).
Hypoglycemia (continued). "With a hypoglycemia threshold of 70 mg/dL, the patient profile included glucose readings, meals, insulin dosage, and physical activity along with additional elements to account for recurrent nocturnal hypoglycemia caused by previous hypoglycemia, exercise, and sleep." (PMID 35862181, 2022). "In an indirect meta-analysis, SGLT2-Is achieved better glycemic control and greater weight reduction than DPP4 inhibitors, without increasing the risk of hypoglycemia in patients with T2DM inadequately controlled with insulin." (PMID 35409011, 2022). "Administration of IGF-1 may induce severe hypoglycemia due to its molecular structure and functional similarity with insulin." (PMID 35847048, 2022). "However, a systematic review with meta-analysis that we judged to be of critically low quality reported a reduced prevalence of hypoglycaemia when lower doses of insulin were compared with standard doses." (PMID 35552566, 2022). "If these parameters are inappropriate, persistent deviations could have occurred, then insulin will be over-delivered, increasing the possibility of hypoglycemia." (PMID 36411933, 2022). "When blood glucose level is low, GLP-1RA have no stimulating effect on insulin secretion, which helps decrease the risk of hypoglycemia." (PMID 35865956, 2022). "The primary rationale for dual-hormone systems, which are capable of administering boluses of glucagon in addition to continuous insulin infusion, is that prevention of hypoglycemia is more effective with administration of glucagon than with suspension of insulin delivery." (PMID 35733769, 2022). "In Chinese trials with T2DM, the addition of linagliptin and insulin improved glycemic control and was well tolerated with no increased risk of hypoglycemia or weight gain." (PMID 35630534, 2022). "This “functional hypercortisolism” by antagonizing insulin actions may prevent hypoglycemia, disturb energy homeostasis, and shift energy fluxes away from muscle toward fat stores." (PMID 35897752, 2022). "After only 6 hours since the test began, the patient experienced symptomatic hypoglycaemia with plasma glucose level went down to 1.6 mmol/L, and his concomitant serum insulin level was 53 mIU/L and C-peptide level was 0.23 nmol/L and pro-insulin level was 3.8 pmol/L." (PMID 36387920, 2022). "While insulin constitutes a beneficial treatment, its use may be limited due to increased degradation and an increase in side effects such as weight gain and hypoglycemia." (PMID 35350789, 2022). "This tiny rise in circulating insulin is not sufficient to cause hypoglycemia or suppress C-peptide levels." (PMID 36134657, 2022). "Recently, it was reported that advanced CKD and insulin therapy are risk factors in type 2 DM patients, and the risk of severe hypoglycemia is not uncommon." (PMID 35755525, 2022). "Rebound hypoglycemia when stopping PN with added insulin is very rare in adults." (PMID 36992742, 2022). "Additionally, a reduced possibility of hypoglycemia, greater satisfaction and in certain cases, and low weightage has been observed through insulin preparations." (PMID 35723344, 2022). "Therefore, the insulin-hypoglycemia test can be used to assess anterior and posterior pituitary functions." (PMID 35723775, 2022). "On the other hand, some gluten-free food items may be low in carbohydrates; hence, hypoglycemia may develop after the administration of standard (unadjusted) dosages of insulin." (PMID 36615856, 2022). "Hypoglycemia was sixteen times more frequent in patients receiving insulin therapy." (PMID 35457586, 2022). "Insulin induced the same level of hypoglycemia in both groups of mice." (PMID 36180454, 2022). "However, traditional insulin secretory agents such as sulfonylureas and glinides have side effects of hypoglycemia." (PMID 36467075, 2022).
Hypoglycemia (continued). "First, we should consider the fact that Kir6.2−/− mice have a complete deficiency of electrophysiological activity of the KATP channel in pancreatic beta cells and present neonatal transient hypoglycemia followed by normoglycemia with a partial reduction of glucose-stimulated insulin secretion." (PMID 35005553, 2022). "Second, the relatively high doses of insulin used in most clamp studies may affect the counterregulatory hormone and symptom responses to hypoglycaemia, which could alter glycaemic thresholds when compared with hypoglycaemia occurring spontaneously." (PMID 35867127, 2022). "Accordingly, automated insulin delivery, also known as the artificial pancreas (AP), has emerged as the best solution to automatically modulate insulin and remove the threat posed by hypoglycemia." (PMID 35265035, 2022). "There may also have been discrepancies or inaccuracies in the self-reported data, such as omission of insulin bolus corrections or hypoglycemia correction." (PMID 36237197, 2022). "Thus, PTEN deficiency in humans enhances insulin signaling, a similar situation to that seen in individuals with repeated episodes of insulin-induced hypoglycemia." (PMID 35406129, 2022). "Recently, however, several scientific studies have been published highlighting the safety and efficacy of low carb diets in the management of DM 1, showing better glycemic control and reductions in insulin requirement, hypoglycemia rates, and reductions in the incidence of diabetic ketoacidosis." (PMID 35956384, 2022). "Participants with fasting glucose <7 mmol/L spent 2.40% (IQR: 0.60–4.98) and 6.52% (IQR: 1.24– 13.50) of their total time per week in hypoglycemia, for SU and insulin, respectively, in comparison with only 0.0% (IQR: 0.00–0.46) and 0.67% (IQR: 0.00–3.44) for those who had fasting glucose ≥7 mmol/L." (PMID 35450869, 2022). "In addition to the main controller focusing on insulin infusion, a fuzzy logic fusion controller was introduced to infuse glucagon based on the identified signals during a hypoglycemia event." (PMID 35200143, 2022). "However, it is believed that the “Somogyi effect” is due to the release of counter-regulatory hormones (such as epinephrine, growth hormone, and cortisol) in response to nocturnal hypoglycemia induced by excessive amounts of exogenous insulin." (PMID 36237834, 2022). "An extensive survey of different analyses examining the earliest long-lasting insulin preparations in contrast with NPH insulin discovered a deduction in the possibility of nighttime hypoglycemia evidence and the hemoglobin A1c extent of subjects using the earlier." (PMID 35723344, 2022). "Moreover, though insulin administration offers some regulatory abilities, many patients develop chronic complications or become disabled by refractory hypoglycemia." (PMID 35324794, 2022). "Twenty‐eight dogs had fasting hypoglycaemia in the presence of a normal or increased insulin level." (PMID 35079406, 2022). "By using SBMG, patients can adjust insulin doses for self-medication and detect hypoglycemia." (PMID 36411933, 2022). "Thus, frequent and close monitoring of hypoglycemia is required when patients initiated with premixed insulin-based therapy." (PMID 35617250, 2022). "In response to the insulin challenge, the PGLs decreased and approached hypoglycemia in 1.5 h." (PMID 35957510, 2022). "As an SGLT2 inhibitor, the glucose-lowering effect of dapagliflozin does not increase the risk of hypoglycemia and is independent of insulin secretion or action." (PMID 36059948, 2022). "Further, HM15136 could effectively reverse acute hypoglycemia induced by insulin challenge, and multiple doses of HM15136 could sustain increased blood glucose levels in CHI rats." (PMID 36202918, 2022). "Therefore, exogenous pyruvate enhances insulin secretion in islet β-cells even in type 1 diabetic patients to the extent of hypoglycemia." (PMID 35991638, 2022).
Hypoglycemia (continued). "Furthermore, hybrid insulin pumps that deliver both insulin and glucagon have recently been introduced to support patients who are unaware of hypoglycemia." (PMID 35324747, 2022). "An inappropriately high serum insulin level was noted in the face of marked hypoglycemia." (PMID 36458207, 2022). "However, the high rate of hypoglycemia represents a major limitation, and the active daily review of insulin dosage is mandatory, which is quite time consuming and requires certain expertise." (PMID 35628938, 2022). "We also investigated the behaviour of the system under hypoglycemia by simulating this condition in silico, and the model could correctly predict the glucose and insulin responses measured in new MPS experiments." (PMID 36260620, 2022). "Accordingly, it was speculated that daily insulin dose, prandial to total insulin ratio and utilization of rapid-acting insulin analogs can influence hypoglycemia." (PMID 36091534, 2022). "Such widely applied treatment can not realize the on-demand release of insulin, leading to the poor patient compliance, and sometimes hypoglycemia, which probably results in the potential risk of brain damage or death." (PMID 36246353, 2022). "In addition, the effects of GV and hypoglycemia on mortality were attenuated yet significant after adjusting for other glycemic metrics, insulin infusion therapy, glucocorticoids use, duration of ventilation, and duration of hemodialysis." (PMID 34761326, 2022). "In male mice, aldometanib elicits an insulin-independent glucose-lowering effect, without causing hypoglycaemia." (PMID 36217034, 2022). "In this study, most of the PCPs (73.6%) reported being unwilling to initiate insulin for patients who do not adhere or are unable to self-monitor their blood sugar, or for those at high risk of hypoglycemia (e.g., the elderly)." (PMID 36554673, 2022). "Hence, in order to prevent hypoglycemia, the dosage of insulin and/or insulin secretagogues have to be lowered when used in conjunction with empagliflozin." (PMID 36147179, 2022). "However, insulin-induced hypoglycemia after NA pre-treatment led to the same plasma glucagon levels in Agpat5flox/flox mice and AgRPAgpat5KO mice." (PMID 36180454, 2022). "Accurate prediction models could also be used in a closed-loop system to suspend insulin dosing in order to avoid severe hypoglycemia." (PMID 36992787, 2022). "Micro-doses of glucagon could be given at the same time as meal boluses of insulin to promote postprandial insulin absorption and larger doses of glucagon may be administered when indicated to treat and prevent hypoglycaemia." (PMID 36213069, 2022). "One problem is that injected insulin can further increase glucose uptake in skeletal muscle and may block glucagon-mediated hepatic glucose production resulting in exercise-induced hypoglycemia." (PMID 36339413, 2022). "Previous studies had demonstrated that intensive insulin treatment or sulfonylurea (SU) could predict the episodes of hypoglycemia in T2DM." (PMID 36443872, 2022). "Although the initiation of different insulin regimens has a significant effect on glycemic control and delays the onset of complications, treating patients without a significant risk of hypoglycemia in the real-world practices remains difficult." (PMID 36149907, 2022). "Therefore, patients initiated with premixed insulin need to be highly vigilant and motivated to recognize the symptoms of hypoglycemia." (PMID 36149907, 2022). "In conclusion, prandial insulin injected before a meal, particularly at breakfast, provides better post-prandial glycemia and HbA1c without increasing the risk of hypoglycemia, and without affecting total daily insulin dose and BMI." (PMID 36556278, 2022). "The question of whether hysteresis in insulin secretion plays a role in postprandial hypoglycemia is also addressed." (PMID 36148302, 2022).